PCSK9 (proprotein convertase subtilisin/kexin type 9)
Diseases named in the same sentence as PCSK9 in open-access papers (continued):
Sharing a sentence is not in itself a finding about the gene and the disease.
Alzheimer disease (35 papers, 2012 to 2026). A progressive, neurodegenerative disease characterized by loss of function and death of nerve cells in several areas of the brain leading to loss of cognitive function such as memory and language. "Previous genetic studies of LDL‐C lowering via PCSK9 reported detrimental effects on risk of Alzheimer's disease and depression." (PMID 37208559, 2023). "Given the small number of ε4/ε4 carriers in this sample, future research is needed to evaluate the effectiveness of PCSK9 inhibitors to reduce the risk of cognitive decline in those most at risk for Alzheimer’s disease." (PMID 35404972, 2022). "Some evidence has suggested an involvement of PCSK9 in Alzheimer’s disease (AD), but the underlying mechanisms are still far from being understood." (PMID 36293049, 2022). "Since VLDLR and ApoER2 are highly expressed in the central nervous system and have been previously implicated in Alzheimer's disease, the role of PCSK9 has been recently investigated in vivo." (PMID 24278757, 2012). "Furthermore, while a targeted reduction in PCSK9 concentrations shows promise in lowering the risk of AF, it is essential to consider the possible increased risks of developing Alzheimer's disease and asthma." (PMID 39781530, 2025). "Furthermore, PCSK9 seems to be directly implicated in key processes associated with the development of Alzheimer's disease, such as inflammation, oxidative stress, and Aβ deposition." (PMID 40354375, 2025). "In Alzheimer’s disease (AD), it is believed that cognitive impairment is associated with cholesterol metabolism alterations, which could involve PCSK9." (PMID 31437157, 2019). "A systematic search was conducted in PubMed, Scopus, ScienceDirect, and Google Scholar (2020–2025) using predefined terms related to PCSK9 and Alzheimer’s disease." (PMID 41465790, 2025). "A vascular perspective, suppressing PCSK9, bolsters the health of blood vessels, offering a crucial neuroprotective effect against Alzheimer’s disease." (PMID 41465790, 2025). "Scientific interest in the role of PCSK9 in Alzheimer’s disease has led to a wide range of research approaches." (PMID 41465790, 2025). "Considering that PCSK9 was initially found in apoptotic neurons, its implication in neurodegenerative diseases, in particular in Alzheimer’s disease (AD) has been extensively scrutinized." (PMID 37586604, 2023). "PCSK9 has been investigated in neurodegenerative disorders such as Alzheimer’s disease, where altered levels of the protein levels in cerebrospinal fluid (CSF) and brain samples have been associated with disease." (PMID 35501368, 2022). "The Proprotein Convertase Subtilisin/Kexin Type 9 (PCSK9) involvement in Alzheimer’s disease (AD) is poorly investigated." (PMID 36293049, 2022). "For example, in Alzheimer’s disease PCSK9 plays a direct role in the brain by lowering BACE1 expression and an indirect role by increasing LDL-C levels, which affects Aβ plaque formation and aggregation." (PMID 32595449, 2020). "In this review article, we will focus on the role of PCSK9 at the cerebral level with particular attention on its potential involvement in neuronal functions and Alzheimer’s disease (AD) pathogenesis." (PMID 31178716, 2019). "On the other hand, in the same study, the effect of low LDL levels and HMGCR and PCSK9 polymorphisms on the risk of disorders such as vascular dementia, Alzheimer’s disease, and Parkinson’s disease was not proven." (PMID 39201649, 2024). "Furthermore, patients with Alzheimer’s disease have higher PCSK9 mRNA and protein levels in their postmortem brains as well as higher cerebrospinal fluid levels of PCSK9." (PMID 35404972, 2022). "In addition, deviations in PCSK9 levels have been correlated with other Alzheimer’s disease biomarkers during the pre-onset stage of the disease." (PMID 32225060, 2020).
Alzheimer disease (continued). "Given the role of PCSK9 in apoptosis, lipoprotein receptor metabolism, and inflammation, PCSK9 might play a regulatory role in Alzheimer’s disease (AD) pathogenesis." (PMID 32595449, 2020). "Moreover, PCSK9 has been shown to regulate levels of BACE1, one of the enzymes that cleaves APP to form the Aβ peptide associated with Alzheimer disease." (PMID 23430252, 2013). "PCSK9 might play a role in Alzheimer’s disease, but the exact mechanisms are yet to be elucidated." (PMID 39337507, 2024). "In addition to PCSK9, expression data highlights the roles of DHCR24 and USP24 in SMI and CMD: DCHR24 has been shown to have a neuroprotective role during inflammation with loss-of DCHR24 expression being observed in Alzheimer’s disease." (PMID 35501368, 2022). "Furthermore, as PCSK9 was first discovered in brain and in patients with Alzheimer’s disease, high concentrations of PCSK9 in cerebrospinal fluid have been found, a role of PCSK9 in Alzheimer’s disease has been controversially discussed." (PMID 33304274, 2020). "Supermeres are highly enriched with cargo involved in multiple cancers (glycolytic enzymes, TGFBI, miR-1246, MET, GPC1 and AGO2), Alzheimer’s disease (APP) and cardiovascular disease (ACE2, ACE and PCSK9)." (PMID 34887515, 2021). "In this regard, we and others previously observed that the cerebrospinal fluid (CSF) of patients affected by Alzheimer’s disease (AD) displays higher concentrations of PCSK9 as compared to non-AD subjects." (PMID 36293049, 2022). "Additionally, a Mendelian randomization study of 111,194 Danish individuals showed that lower LDL cholesterol levels due to PCSK9 LOF variants rs11591147, rs148195424, and rs562556 did not increase the risk of Alzheimer’s disease, and instead may have a causal effect in reducing the risk of AD." (PMID 32595449, 2020).
heart failure (33 papers, 2017 to 2025). Inability of the heart to pump blood at an adequate rate to meet tissue metabolic requirements. "A higher plasma PCSK9 level is associated with an increased risk of all-cause mortality in patients with heart failure (HF)." (PMID 40076547, 2025). "There are also reports of an association between these PCSK9 genetic variants and the risk of developing metabolic disorders, t.2 diabetes, obesity, and heart failure with preserved ejection fraction (HFpEF)." (PMID 38886277, 2024). "It has also been reported that PCSK9 deficiency can potentially impact cardiac lipid metabolism, contributing to the plausible development of heart failure." (PMID 36771126, 2023). "We demonstrate that cardiomyocyte expression of Pcsk9 contributes to normal mitochondrial function and that CM-Pcsk9−/− is linked to heart failure." (PMID 36880401, 2023). "Additionally, the investigators discovered a significant association between PAI-1 and PCSK9 levels in people with heart failure, pointing to a possible interaction between PCSK9 and the fibrinolytic process." (PMID 37765005, 2023). "In patients with heart failure, PCSK9 levels predict the risk of mortality." (PMID 37620933, 2023). "Univariate Cox regression analysis revealed a significant association between high PCSK9 levels and increased risk of MACEs or rehospitalization for heart failure in the whole cohort (HR: 1.420, 95% CI 1.033–1.953, P = 0.031; HR: 2.463, 95% CI 1.011–5.988, P = 0.047; respectively)." (PMID 35596184, 2022). "In line with this, plasma concentration of PCSK9 is associated with heart failure." (PMID 33364976, 2020). "Therefore, oxLDL is not only a biomarker associated with oxidative stress, cardiac dysfunction and heart failure but it plays an active role in this process and PCSK9 exerts important direct cardiac effects." (PMID 28913715, 2017). "Notably, a study reported that systemic proprotein convertase subtilisin/kexin type 9 (PCSK9) deficiency reduced LDL-C levels but results in heart failure with preserved ejection fraction associated with changed in cardiac metabolism and increased cardiac accumulation of lipid droplets (LDs)." (PMID 39476450, 2024). "In this study, we showed that cardiomyocyte-specific deletion of Pcsk9 in mice caused a progressive dilated cardiomyopathy-like phenotype characterized by cardiomyocyte hypertrophy, interstitial fibrosis, and contractile dysfunction, culminating in heart failure and premature death." (PMID 36880401, 2023). "Clinical studies have recently shown that circulating PCSK9 levels are significantly higher in patients with heart failure (HF), mainly heart failure with reduced ejection fraction (HFrEF)." (PMID 38886277, 2024). "Reduced PCSK9 expression in the myocardium resulted in signs of heart failure, left ventricular dilatation, myocardial interstitial fibrosis, and pulmonary congestion in middle-aged mice (28 weeks old), ultimately leading to mortality within 8 weeks." (PMID 39139638, 2024). "Conversely, another study found that the cardiac-specific knockout of PCSK9 led to the development of heart failure with preserved ejection fraction (HFpEF)." (PMID 38383373, 2024). "Complete knockout of PCSK9 in mice is deleterious, even leading to heart failure with preserved ejection fraction (HFpEF)." (PMID 36970356, 2023). "Detrimental events such as hypoxia, acute inflammation, and heart failure can induce different types of cardiomyocyte cell death through PCSK9 overexpression." (PMID 36900189, 2023). "Its deficiency has been observed to affect heart metabolism and function, potentially leading to heart failure with preserved ejection fraction (HFpEF), indicating a strong link between PCSK9 and lipid metabolism in the cardiovascular system." (PMID 38144368, 2023). "Genetic studies associated loss of function mutation in PCSK9 gene with high LDL levels and high rates of heart failure." (PMID 36900189, 2023).
heart failure (continued). "Furthermore, the serum level of PCSK9 is positively correlated with mortality in patients with heart failure (HF)." (PMID 40076547, 2025). "PCSK9 induces the expression of pro-inflammatory cytokines contributing to inflammation within the vascular wall and promotes apoptosis, pyroptosis, and ferroptosis of cardiomyocytes and is thus involved in the development and progression of heart failure." (PMID 38886277, 2024). "Fortunately, in large clinical trials, PCSK9 inhibitors are tolerated and effectively, without the increased risk of heart failure." (PMID 36970356, 2023). "Moreover, it is conceivable that PCSK9 has a role in heart failure, hypertrophy, and cardiac fibrosis." (PMID 36900189, 2023). "Furthermore, the authors also found a positive correlation between PAI-1 and PCSK9 levels in patients with heart failure, suggesting an interplay between the fibrinolytic process and PCSK9." (PMID 35323669, 2022). "No PCSK9 GS association was observed with atrial fibrillation (OR 0.92 95% CI 0.72; 1.18; 41,485 cases), or heart failure (OR 1.06 95% CI 0.48; 2.32; 1803 cases)." (PMID 31664920, 2019). "However, in another extensive nested case-control study, PCSK9 LOF carriers displayed left ventricular size, ejection fraction, and heart failure prevalence comparable to those in normal individuals." (PMID 39139638, 2024). "In patients with a history of heart failure and a recent acute coronary syndrome, treatment with the PCSK9-antibody Alirocumab did not lead to a reduction in cardiovascular events despite potent LDL cholesterol reduction." (PMID 39906341, 2024). "The absence of PCSK9 within the myocardium leads to disruption of lipid metabolism, myocardial dysfunction, and potential heart failure." (PMID 39139638, 2024).
melanoma (32 papers, 2013 to 2025). A malignant, usually aggressive tumor composed of atypical, neoplastic melanocytes. "Conversely, PCSK9 gene expression was linked to an elevated melanoma risk [OR: 1.233 (1.026–1.484); p = 0.025]." (PMID 38974243, 2024). "Conversely, PCSK9 gene expression is tied to an elevated risk of melanoma [OR: 1.233(1.026–1.484); p = 0.025]." (PMID 38974243, 2024). "Although melanomas (and many other cancer types) show the association between elevated PCSK9 expression and risk of poor OS, the dominant approach utilized in PCSK9-related cancer studies was mainly via its downregulation." (PMID 36588164, 2023). "Additionally, MR Egger [OR: 1.386 (1.067–1.802); p = 0.014] and weighted median [OR: 1.300 (1.038–1.628); p = 0.023] analyses indicated that PCSK9 expression increases melanoma risk." (PMID 38974243, 2024). "HMGCR inhibitors (statins) may increase melanoma risk, while PCSK9 inhibitors (evolocumab, alirocumab) could potentially decrease melanoma risk." (PMID 38974243, 2024). "Our investigation revealed an association between PCSK9 gene expression and an increased risk of melanoma, suggesting that PCSK9 inhibitors, which reduce LDL-C levels, may offer a specific protective effect against melanoma." (PMID 38974243, 2024). "Their results confirmed that PCSK9 deficiency could reduce the metastasis of melanoma in the livers of mice." (PMID 39736777, 2024). "PCSK9’s association with melanoma was analysed using the TCGA dataset." (PMID 36588164, 2023). "PCSK9-derived oncogenesis in melanoma is closely associated with lipid accumulation." (PMID 36588164, 2023). "Empty vector (EV), PCSK9, gain-of-function (D374Y), and loss-of-function (Q152H) PCSK9 mutant were stably-expressed in murine melanoma B16 cells and studied for impact on B16 cell-derived oncogenesis in vitro and in vivo using syngeneic C57BL/6 and Pcsk9−/− mice." (PMID 36588164, 2023). "PCSK9-deficient melanoma cells were also shown to be highly susceptible to CTL killing in vitro." (PMID 33677469, 2021). "Indeed, it was reported that PCSK9 deficiency reduces melanoma metastasis in liver, and that PCSK9 enhances metastasis of melanoma-derived cells into lung epithelial cells." (PMID 34606887, 2021). "However, the relevance of these two actions and the mechanisms underlying PCSK9’s oncogenic roles in melanoma and other cancers remain unclear." (PMID 36588164, 2023). "Animal experiments have also shown that inhibiting PCSK9 can suppress liver metastasis of melanoma in mice and enhance the efficacy of immunotherapy." (PMID 40872487, 2025). "Conversely, high PCSK9 expression correlates with worse OS in bladder cancer, renal clear cell carcinoma, melanoma, and pancreatic cancer." (PMID 40576911, 2025). "They injected B16F1 melanoma cells into PCSK9 KO mice to induce liver metastasis and found that the mice had a low risk of developing liver metastases, which correlated with cholesterol levels." (PMID 39736777, 2024). "A subcutaneous tumor model of B16F10-OVA melanoma was established and treated by the PCSK9 inhibitor and OVA-II peptide vaccines." (PMID 38600469, 2024). "Existing studies highlight the significant role of PCSK9 expression in melanoma’s pathogenesis, particularly noting the critical contribution of cholesterol accumulation in tumors facilitated by PCSK9." (PMID 38974243, 2024). "PCSK9 inhibitors emerge as potential protective agents against melanoma, highlighting their promise as therapeutic options." (PMID 38974243, 2024). "PCSK9’s role in melanoma progression, through its impact on lipid metabolism and the immune system, has been highlighted in vitro studies." (PMID 38760735, 2024).
melanoma (continued). "Employing Mendelian randomization, we investigated the impact of three prevalent LDL-C reduction drug targets (HMGCR, PCSK9, and NPC1L1 genes) on melanoma risk." (PMID 38974243, 2024). "Our findings indicate that existing PCSK9 inhibitors, such as alirocumab and evolocumab, can influence melanoma by targeting LDL-related sites within the gene, thereby supporting the repurposing of these drugs." (PMID 38760735, 2024). "Nonetheless, our study suggests the focus should be on tumor-derived PCSK9 instead of PCSK9 in circulation, as tumor-produced PCSK9 appears to be much more critical than the host or circulating PCSK9 in facilitating melanoma." (PMID 36588164, 2023). "PCSK9 expression and its network negatively correlated with the survival probability of patients with melanoma." (PMID 36588164, 2023). "We provide the first evidence for PCSK9 facilitating melanoma pathogenesis via enhancing intratumoral cholesterol accumulation." (PMID 36588164, 2023). "We present here a comprehensive set of indirect evidence in favor of PCSK9 facilitating melanoma at least in part via regulating lipid/cholesterol metabolism." (PMID 36588164, 2023). "Overlap of 36 genes between the D374Y DEGs and the PCSK9 DEGs predicted poor prognosis of melanoma and resistance to immune checkpoint blockade (ICB) therapy." (PMID 36588164, 2023). "In a mice study, PCSK9 expression was shown to be involved in the metastasis process of melanoma cells into lung epithelial cells, while study of the human lung cells found that PCSK9 had an anti‐apoptotic effect on cancer cells." (PMID 37208559, 2023). "Another preclinical study in melanoma-bearing mice concluded that PCSK9 gene silencing significantly increases the response to ICIs." (PMID 36900189, 2023). "Overlap36sub was derived from DEGs shared by PCSK9 and D374Y tumors, which highlights the relevance of PCSK9 network derived from B16 tumors to melanoma progression." (PMID 36588164, 2023). "This property along with the observations that both PCSK9 and D374Y promote tumor growth supports these genes contributing to melanoma pathogenesis." (PMID 36588164, 2023). "It is thus tempting to propose that the actions of the GAS6/AXL signaling contribute to PCSK9-initiated immunosuppressive TME in melanoma." (PMID 36588164, 2023). "The molecular details responsible for PCSK9 to facilitate melanoma in the utilization of cholesterol need further investigations." (PMID 36588164, 2023). "In melanoma, colon and breast murine cancer cells, the inhibition of PCSK9 synergistically boosted the tumor response to murine anti-PD1 immune checkpoint inhibitor, resulting in the suppression of tumor growth." (PMID 36552895, 2022). "Recently, PCSK9 was found to inhibit cell apoptosis in a variety of tumors, such as neuroglioma, lung adenocarcinoma, melanoma, and neuroendocrine neoplasms." (PMID 33789749, 2021). "One study showed that PCSK9 neutralization improved the efficacy of ICI in melanoma in a mouse model." (PMID 34356899, 2021). "Not only in HCC, researchers have confirmed that PCSK9 can influence the apoptosis of other tumors, such as neuroglioma, lung adenocarcinoma, melanoma, and neuroendocrine neoplasms." (PMID 33789749, 2021). "Recently, we observed that PCSK9 enhances the ability of mouse melanoma B16 cells to colonize liver in a metastasis model." (PMID 23675525, 2013).